PACC1 (proton activated chloride channel 1)
Description:
Chloride channel gated by pH that facilitates the entry of chloride ions into cells upon exposure to extracellular acidic pH. Involved in acidosis-induced cell death by mediating chloride influx and subsequent cell swelling.
Synonyms: PAC; hPAC; ASOR; PAORAC; hTMEM206; C1orf75; TMEM206; FLJ10874
Tractability: Small molecule: a structure with a bound ligand is known. Antibody: UniProt places it where antibodies can reach, with high confidence; its Gene Ontology location is reachable by antibodies, with high confidence; UniProt predicts a signal peptide or a membrane-spanning region. PROTAC: ubiquitination databases record sites on it.
Gene: Protein-coding gene on chromosome 1 (212,363,926 to 212,414,909, reverse strand). Ensembl gene ENSG00000065600.
Subcellular location: Cell membrane
Gene Ontology:
Molecular function: pH-gated chloride channel activity; protein binding
Biological process: chloride transport; chloride transmembrane transport
Cellular component: cell surface; plasma membrane
Genetic constraint (gnomAD): Loss-of-function variants: 32 observed, 39.55 expected, observed/expected ratio (o/e) 0.81, 90% interval 0.61 to 1.09. The synonymous counts are far from expectation, so gnomAD's model fits this gene poorly and the ratio says little. Missense variants: 374 observed, 449.17 expected, observed/expected ratio (o/e) 0.83, 90% interval 0.76 to 0.91. Synonymous variants: 127 observed, 166.76 expected, observed/expected ratio (o/e) 0.76, 90% interval 0.66 to 0.88.
Homologues: Orthologues: chimpanzee PACC1 (99% identical), macaque PACC1 (98% identical), dog PACC1 (94% identical), pig PACC1 (91% identical), guinea pig PACC1 (91% identical), rat Pacc1 (91% identical), mouse Pacc1 (91% identical), rabbit PACC1 (90% identical), tropical clawed frog pacc1 (65% identical), zebrafish pacc1 (54% identical).
Diseases named in the same sentence as PACC1 in open-access papers:
PACC1 is named in the same sentence as 28 diseases in open-access papers, as found by Europe PMC text mining. Sharing a sentence is not in itself a finding about the gene and the disease. The quoted sentences say what the papers report.
colorectal cancer (7 papers, 2019 to 2024). A primary or metastatic malignant neoplasm that affects the colon or rectum. "The TMEM206/PACC1 gene is involved in the progression of colorectal cancer by accelerating cell proliferation and promoting cell migration and invasion." (PMID 35884425, 2022).
breast carcinoma (1 paper, 2022). "Among these genes, ZFAND1, TYRO3, and TMEM206/PACC1 showed evidence of association with LoF variants for overall breast cancer." (PMID 35884425, 2022). "Of these twenty, three showed evidence of association with LoF variants for overall breast cancer (ZFAND1, TYRO3, TMEM206/PACC1), and a further six with breast cancer subtypes (DNAH11, PARP2, LAMC3, MTMR11, EPN3, SLC22A10)." (PMID 35884425, 2022). "We found nominal evidence of association with breast cancer overall for LoF variants in three genes (ZFAND1, TMEM206/PACC1, and TYRO3), with ER-negative breast cancer in two genes, DNAH11 and PARP2, and with ER-positive disease in four genes LAMC3, MTMR11, EPN3, and SLC22A10." (PMID 35884425, 2022).
Cerebellar atrophy (1 paper, 2021). Cerebellar atrophy is defined as a cerebellum with initially normal structures, in a posterior fossa with normal size, which displays enlarged fissures (interfolial spaces) in comparison to the foliae secondary to loss of tissue. "Our studies suggest RDH14 as a candidate for autosomal recessive ID and cerebellar atrophy, implicating either disrupted retinoic acid signaling, or, through PACC1, disrupted chloride ion homeostasis in the brain as a putative disease mechanism." (PMID 34848785, 2021).
cancer (12 papers, 2019 to 2025). A tumor composed of atypical neoplastic, often pleomorphic cells that invade other tissues. "The results of this study show that in the DFS analysis of PACC1 in TNBC patients, the high expression of PACC1 will lead to significant adverse prognostic effects, which may be related to the high expression of PACC1 inducing the proliferation and metastasis of cancer cells." (PMID 35627287, 2022).
PACC1 also shares sentences with these, for which no sentence is quoted: tumor (5 papers); prostate carcinoma (3); colon cancer (2); dental caries (2); infection (2); ischemic stroke (2); osteosarcoma (2); acute myeloid leukemia (1); bladder cancer (1); colorectal tumors (1); corneal edema (1); gastric cancer (1); glioblastoma (1); hepatocellular carcinoma (1); influenza (1); liver cancer (1); lung carcinoma (1); lymphoma (1); medulloblastoma (1); neurodegenerative disease (1); non-Hodgkin lymphoma (1); osteopetrosis (1); pancreatic cancer (1); Stroke (1).